INS (insulin)
Diseases named in the same sentence as INS in open-access papers (continued):
Sharing a sentence is not in itself a finding about the gene and the disease.
type 1 diabetes (continued). "One hypothesis suggests that low bone mass results from insulin insufficiency in type-1 diabetes, but increasing insulin levels in individuals with T2D may increase BMD because insulin signals the bone’s osteoblasts to become more active." (PMID 38654244, 2024). "Two or more autoantibodies against either insulin (IAA), glutamic acid decarboxylase (GADA), islet antigen-2 (IA-2A) or zinc transporter 8 (ZnT8A) denote stage 1 (normoglycemia) or stage 2 (dysglycemia) type 1 diabetes prior to stage 3 type 1 diabetes." (PMID 38723553, 2024). "We infer that PC1/3-mediated prohormone processing is impaired in beta cells in donors with type 1 diabetes, as the percentage of PC1/3-positive and insulin-positive cells in islets is reduced, and the co-localisation of PC1/3 and insulin at the subcellular level is significantly decreased." (PMID 39404844, 2024). "The clinical features of autoimmune diabetes mellitus are similar to those of fulminant type I diabetes mellitus, including rapidly increasing blood glucose, often leading to ketoacidosis, lack of endogenous insulin, and low or undetectable C-peptide levels." (PMID 38577606, 2024). "This is in contrast to guidelines from the UK, which suggest that insulin should never be discontinued for those who have type 1 diabetes." (PMID 39390487, 2024). "Considering the necessity of insulin therapy in the GDM group, women with the TT genotype were more likely to develop insulin-dependent diabetes (45.5%) compared to other genotypes ((22.7%—CC genotype, 31.8%—CT genotype) OR 5.67 [CI 95% 1.61–19.97], p = 0.005)." (PMID 38612849, 2024). "In individuals with type 1 diabetes, the body produces minimal or no insulin due to the immune system attacking and destroying the insulin-producing cells in the pancreas." (PMID 39851278, 2024). "The median proinsulin/insulin ratio was significantly reduced in islets from donors with type 1 diabetes (1.009 vs 0.823 vs 0.171 for non-diabetic donors vs donors with short-duration type 1 diabetes vs donors with long-duration type 1 diabetes)." (PMID 39404844, 2024). "Type 1 diabetes (T1D) represents a chronic autoimmune disease demanding continuous efforts and adherence to blood glucose measurements and/or continuous glucose monitoring (CGM), insulin dosing, and carbohydrate counting in order to maintain glycemic control." (PMID 39329826, 2024). "Insulin treatment stands as a cornerstone for individuals grappling with type 1 diabetes, given the characteristic absence or near-absence of β-cell function in this population." (PMID 39065795, 2024). "This was accomplished by evaluating the ability of HOMA-IR or Matsuda Index to predict stages of type 1 diabetes development, with and without adjustments for indicators of insulin secretion." (PMID 37914981, 2024). "The blood glucose level cannot remain within the normal range in patients with type 1 diabetes because they do not produce insulin." (PMID 39055230, 2024). "Persons with type I diabetes have a pancreas that either does not make any insulin at all or makes inadequate amounts of it." (PMID 39771551, 2024). "On the other hand, the study benefits from a well-characterized cohort of Finnish participants with type 1 diabetes, and strict exclusion criteria such as non-smoking status, absence of diabetic complications, and no medications other than insulin use." (PMID 39342285, 2024). "Type 1 diabetes is an autoimmune disease in which the body does not produce any insulin because the beta cells that secrete insulin are destroyed by autoimmunity." (PMID 39840001, 2024). "It has been shown that in a mouse model of type 1 diabetes, the absence of senescent β cells enhances insulin secretion and preserves insulin secretory capacity, thus establishing a new link between cellular senescence and severe insulin deficiency." (PMID 38421832, 2024).
type 1 diabetes (continued). "While the percentage of insulin, proinsulin and PC1/3 triple-positive cells in islets is significantly reduced in donors with type 1 diabetes, the expression levels of insulin and proinsulin in the remaining beta cell population further declines in donors with long-duration type 1 diabetes." (PMID 39404844, 2024). "In the KEGG analysis, processes such as “Cytokine-cytokine receptor interaction”, “Rheumatoid arthritis”, “Toll-like receptor signaling pathway” and “Type I diabetes mellitus” were upregulated, while “PPAR signaling pathway”, “Tyrosine metabolism” and “Insulin signaling pathway” were downregulated." (PMID 39749331, 2024). "In the absence of exogenous insulin or in the presence of precipitating illnesses, patients with type 1 diabetes (T1DM) can develop diabetic ketoacidosis (DKA), the most serious diabetic emergency that carries a high morbidity and mortality burden." (PMID 38249432, 2024). "Type 1 diabetes (T1D) is attributable to an absolute lack of insulin due to the autoimmune-mediated destruction of the pancreatic beta (β) cells, with hyperglycaemia presenting when more than 90% of the β-cells are lost." (PMID 39022651, 2024). "T1D or insulin-dependent diabetes is a chronic condition where the pancreas makes little or no insulin, as a result of dysfunction of pancreatic, insulin-secreting β-cells." (PMID 38920642, 2024). "Type 1 diabetes is a chronic disease in which the pancreas no longer produces insulin, the hormone critical for blood glucose homeostasis." (PMID 38831294, 2024). "PC1/3 fluorescence intensity, however, was not significantly reduced in the triple-positive cells and insulin-negative cells from donors with type 1 diabetes." (PMID 39404844, 2024). "This is supported by previous research showing that a 25% dose reduction of insulin degludec on 5 consecutive days did not protect against hypoglycaemia during the first 48 h after exercise in people with type 1 diabetes." (PMID 36879098, 2023). "Atypical young-onset diabetes, including patients with the type 1 diabetes phenotype but who do not appear to have the absolute insulin requirement seen in classical type 1 diabetes, has been reported in African populations." (PMID 36778553, 2023). "In type 1 diabetes, almost no endogenous insulin is secreted due to the dysfunction of the insulin-producing beta cells." (PMID 37239172, 2023). "Type I diabetes mellitus requires insulin administration because of the lack of blood sugar control." (PMID 37111730, 2023). "Considering the adverse effects and lack of effectiveness with the current insulin therapy, there has been an increase in search of other potential oral hypoglycaemic or safer natural products for the prevention of type 1 diabetes." (PMID 37528147, 2023). "Since the patient was aware that weight gain is a potential side-effect of insulin, it was important that the team appropriately manage her anorexia, so she would not discontinue her prescribed insulin despite her new diagnosis of insulin-dependent diabetes." (PMID 37855110, 2023). "Our data indicate that during progression to stage 3 type 1 diabetes, rates of change in declining glucose and insulin sensitivity are not significantly different between progressors aged <14 years and progressors aged ≥14 years." (PMID 36459177, 2023). "The two other participants failing the switch attempt (carriers of p.Gly306Val and p.Pro580Leu) revealed almost no insulin secretion, both showing a type 1 diabetes phenotype, and one developed elevated GADA during the study period." (PMID 37798422, 2023). "There is an almost complete lack of insulin in type 1 diabetes, which acts as an anabolic hormone with multiple effects on sugar, lipid, protein metabolism, growth and development." (PMID 36761194, 2023).
type 1 diabetes (continued). "While automated insulin delivery (AID) systems aim to improve glycemic outcomes, the opportunity to improve psychosocial outcomes is also of critical importance for children and adolescents with type 1 diabetes and their caregivers." (PMID 40303234, 2023). "Some clinical observations and studies have reported the existence of groups of people with “type 1 diabetes” like phenotype who are insulin-requiring but can interrupt their routine insulin treatment without developing severe metabolic complications." (PMID 36778553, 2023). "Impaired awareness of hypoglycemia (IAH) is a common acquired condition in which autonomic hypoglycemia-related warning symptoms are reduced or absent in insulin-treated people with Type 1 diabetes (T1D)." (PMID 40303242, 2023). "Type 1diabetes (T1D) is autoimmune, chronic disease characterized by a lack of insulin due to an autoimmune destruction of the insulin-producing beta cells in the pancreas." (PMID 36941696, 2023). "Additional non-HLA genes, namely, INS, PTPN22, and CTLA4, have also been associated with the development of type 1 diabetes." (PMID 37724233, 2023). "The primary treatment for patients with type 1 diabetes mellitus (T1D) consists of the combination of glucose monitoring coupled with daily exogenous insulin injections that, despite their effectiveness, do not prevent the challenges associated with daily compliance and T1D secondary complications." (PMID 36797282, 2023). "Many adults with type 1 diabetes do not achieve recommended glycemic goals despite intensive insulin therapy using insulin pumps." (PMID 37160785, 2023). "Type I diabetes involves a lack of insulin availability which leads to downregulation of the mTORC1 pathway." (PMID 38040743, 2023). "Further, we did not consider adherence to a gluten free diet which, in youth with coexisting type 1 diabetes and CD, leads to regular growth and stable BMI, without any negative effect on HbA1c and insulin requirements." (PMID 37338603, 2023). "This risk for ketoacidosis can be simply mitigated by not using SGLT2 inhibitors in individuals with type 1 diabetes and ensuring that insulin doses are not omitted in insulin-treated patients with T2D." (PMID 37159343, 2023). "For example, some scientists generated a CAR against human insulin and found that the Treg cells were suppressive and long-lived, but did not prevent type 1 diabetes (T1D) in mice." (PMID 37205097, 2023). "INS-DRiP-reactive CTLs that were isolated from individuals with type 1 diabetes would therefore not be able to cross-react with INS-splice." (PMID 36884057, 2023). "Despite decades of research, no treatment exists to cure or prevent type 1 diabetes, and patients still rely on daily, lifelong insulin administration to survive." (PMID 37458220, 2023). "Despite the advances in technology and insulin delivery over the past several decades, less than a third of adults with type 1 diabetes in England and Wales achieve a target HbA1c of ≤58 mmol/mol [7.5%], and only 20% of patients in the US T1D Exchange Registry achieved HbA1c ≤53 mmol/mol [7.0%]." (PMID 37505282, 2023). "Type 1 diabetes mellitus (DM I) is a chronic condition in which the pancreas produces little or no insulin, leading to hyperglycemia." (PMID 36767617, 2023). "Autoantibody-positive (commonly GADA) adult cohorts defined by initial non-insulin-based therapy have previously been described as having latent autoimmune diabetes of adults (LADA), but more recently as having slowly evolving, immune-mediated diabetes of adults." (PMID 37439792, 2023). "Type 1 DM (also known as juvenile diabetes or insulin-dependent diabetes) is a chronic condition in which the pancreas produces little or no insulin." (PMID 38006021, 2023). "In type I diabetes, insulin treatment is necessary because the pancreas does not produce this hormone at all." (PMID 38276837, 2023).
type 1 diabetes (continued). "A previous real-world study on SGLT2i therapy showed a promising reduction in HbA1c, weight and insulin requirements in type 1 diabetes but did not present long-term safety or reno-cardiovascular outcome data." (PMID 37505282, 2023). "Currently, SGLT2 inhibitors as an adjunct therapy to insulin are still not approved for type 1 diabetes." (PMID 37374037, 2023). "There was no differentiation in the studiesbetween insulin- and non-insulin dependent diabetes or the level of diabeticcontrol." (PMID 37727928, 2023). "For instance, due to the lack of insulin and C-peptide secretion in type 1 diabetes, it has been proposed that C-peptide can directly reduce lesions, apply anti-fibrotic and anti-apoptotic effects, and perform as a protective marker." (PMID 37568168, 2023). "In people with type 1 diabetes, Automated Insulin Delivery (AID) systems adjust insulin delivery in response to sensor glucose data and consist of three components: an insulin pump, a continuous glucose sensor, and an algorithm that determines insulin delivery." (PMID 37511644, 2023). "However, the integration of real‐time continuous glucose measurement (rtCGM) data with continuous insulin infusion systems has radically changed the therapeutic approach to type 1 diabetes mellitus (T1D) by providing a major change in the proportion of patients achieving glycemic control targets." (PMID 37337407, 2023). "Hypoglycemia is often seen in type 1 diabetes from taking too much insulin, or not consuming sufficient quantities of carbohydrates for the insulin being taken, or timing of insulin administration and physical activity." (PMID 37538198, 2023). "Insulin was discovered in 1921 and has been in use to treat and save many people with type 1 diabetes (T1D), with little or no insulin production." (PMID 37242426, 2023). "Previously, oral insulin therapy at a modest daily dose of 7.5 mg did not delay progression to type 1 diabetes in first-degree relatives with insulin autoantibodies and ICA, except for a subgroup of relatives with high levels of insulin antibodies." (PMID 37297566, 2023). "There is minimal data of health outcomes for Type 1 Diabetes (T1D) in Southeast Asia (SEA) where government funding of insulin and blood glucose monitoring either do not exist or is limited." (PMID 37974071, 2023). "Early presymptomatic stages of the disease are diagnosed by the detection of multiple islet autoantibodies, including autoantibodies against insulin (IAA), GAD (GADA), IA-2 (IA-2A) and ZnT8 (ZnT8A), and are defined as stage 1 (normoglycaemia) or stage 2 (dysglycaemia) type 1 diabetes." (PMID 37329450, 2023). "In the current study, those who were not insulin-dependent diabetics and utilized insulin as a pharmacological suicide agent were either health professionals or had a relative/partner who had been prescribed insulin." (PMID 35943711, 2022). "Our findings are especially valuable,because they were proven on a specific population of patiens with type 1 diabetes, without endogenous insulin secretion." (PMID 35429987, 2022). "Type 1 diabetes: it is a condition in which the pancreas cannot produces enough insulin or does nor produces any insulin." (PMID 35433625, 2022). "The newly-revised edition of Chinese Insulin Pump Clinical Guideline (2021) has listed type 1 diabetes as an indication with no special recommendation or restriction by age or glycaemic control." (PMID 35757419, 2022). "Theoretically, if an impact of—for instance—insulin should have been examined, the reference population should include children born to fathers with type 1 diabetes not treated with insulin, and such a study will never be performed." (PMID 36362820, 2022). "According to a recent Algerian survey, 69.1% of type 1 diabetics obtained insulin education, but the degree of that education was not mentioned." (PMID 35573427, 2022). "Type 1 Diabetes Mellitus (T1D) is a chronic disease in which the pancreas produces little or no insulin." (PMID 35621461, 2022).
type 1 diabetes (continued). "For insulin-dependent diabetics, an undiagnosed history of depression with or without suicidal ideation is particularly problematic as those on insulin therapy have access to a potentially lethal pharmacological suicide agent." (PMID 35943711, 2022). "People with type 1 diabetes do not routinely give bolus insulin for dietary fat because it does not directly digest into glucose, and therefore is theoretically an attractive way to increase caloric intake." (PMID 36425473, 2022). "A series of intervention studies aimed at preservation of the endogenous insulin secretion have been performed in patients with recent-onset type 1 diabetes over the years with no longstanding results." (PMID 36171903, 2022). "Type 1 diabetes (T1D) is a chronic disease characterized by inadequate or absent insulin production due to the autoimmune destruction of beta (β) cells in the pancreas." (PMID 36042996, 2022). "Patients with the type 1 diabetes require life-saving insulin for as long as they stay alive, though, for the type 2, most of them do not need insulin." (PMID 36236367, 2022). "The activity of SGLT2 inhibitors is independent of insulin status, i.e. undiminished by insulin resistance or absolute insulin lack, enabling glucose lowering in type 2 and type 1 diabetes." (PMID 35113333, 2022). "Type 1 diabetes (T1D) is an autoimmune disease resulting from the destruction of β islet cells, leading to a lack of insulin production." (PMID 35656360, 2022). "Unlike type 1 diabetes, individuals with type 2 diabetes do have β-cells present, but insufficient insulin secretion to control glucose levels." (PMID 35055576, 2022). "From the literature, the majority of individuals with type 1 diabetes report a lack of practical advice for preventing exercise-induced hypoglycemia, with many feeling uneducated about required dose adjustments to insulin and carbohydrate around exercise." (PMID 34427840, 2022). "Type 1 diabetes is a complex disease characterized by the lack of endogenous insulin secreted from the pancreatic β-cells." (PMID 36309486, 2022). "Type 1 diabetes (T1DM) is caused by the nutrition system’s destruction of cells, which results in a lack of insulin production." (PMID 35268815, 2022). "One can also convert physical activity into units of insulin by using the Physical activity to Insulin Ratio, the PIR, to better understand the effects of physical activity on the body and relate it to a known variation in type 1 diabetes patients." (PMID 35577814, 2022). "The previous study shows that in insulin-dependent diabetes testosterone synthesis and function of Leydig cells are decreased due to the lack of insulin, thus reducing LH levels, sperm output, fertility, and FSH." (PMID 36317103, 2022). "Type 1 diabetes is characterized by little or no insulin production owing to complete or partial autoimmune destruction of the insulin-producing pancreatic β-cells." (PMID 36618686, 2022). "Patients with type 1 diabetes who used adjuvant medications with insulin did not have significant improvement in A1C between 2010–2012, 2015–2016, and 2016–2017, when compared to an insulin-only cohort." (PMID 36005937, 2022). "In contrast, a lack of both mature and immature insulin, as observed in the context of type 1 diabetes, leads to severe catabolism." (PMID 35963866, 2022). "An analysis of 20 individuals with type 1 diabetes and FGM showed the worst increase in glucose levels after vaccination in elderly patients on oral hypoglycemic medication (metformin and dapagliflozin) and basal–bolus insulin regimen." (PMID 35745596, 2022). "Additionally, in children with type 1 diabetes, increased serum PCS concentration can be used to monitor the effect of insulin therapy." (PMID 36497042, 2022). "When a person has type-1 diabetes, his or her body generates very little or no insulin, necessitating daily insulin injections to keep blood glucose levels in check." (PMID 35875742, 2022).